CDH4 (cadherin 4)
Description:
Cadherins are calcium-dependent cell adhesion proteins. They preferentially interact with themselves in a homophilic manner in connecting cells; cadherins may thus contribute to the sorting of heterogeneous cell types. May play an important role in retinal development.
Synonyms: R-CAD; CAD4; RCAD
Tractability: Antibody: its Gene Ontology location is reachable by antibodies, with high confidence; UniProt places it where antibodies can reach, with medium confidence; UniProt predicts a signal peptide or a membrane-spanning region; the Human Protein Atlas places it where antibodies can reach. PROTAC: ubiquitination databases record sites on it; its protein half-life has been measured.
Gene: Protein-coding gene on chromosome 20 (61,252,261 to 61,940,617, forward strand). Ensembl gene ENSG00000179242.
Subcellular location: Cell membrane
Subcellular location (Human Protein Atlas): Plasma membrane
Pathways (Reactome):
Cell-Cell communication: Adherens junctions interactions
Developmental Biology: Myogenesis
Gene Ontology:
Molecular function: beta-catenin binding; cadherin binding; calcium ion binding
Biological process: adherens junction organization; calcium-dependent cell-cell adhesion; cell adhesion; cell migration; cell morphogenesis; cell-cell adhesion mediated by cadherin; cell-cell junction assembly; cell-cell adhesion; homophilic cell-cell adhesion
Cellular component: plasma membrane; adherens junction; catenin complex; membrane
Genetic constraint (gnomAD): Loss-of-function variants: 33 observed, 82.85 expected, observed/expected ratio (o/e) 0.4, 90% interval 0.3 to 0.53. The upper end of that interval is the gene's LOEUF score, 0.53, which puts it in group 2 of 6, group 1 being the genes least tolerant of losing a copy. Missense variants: 1,066 observed, 1,285.3 expected, observed/expected ratio (o/e) 0.83, 90% interval 0.79 to 0.87. Synonymous variants: 537 observed, 537 expected, observed/expected ratio (o/e) 1, 90% interval 0.93 to 1.07.
Homologues: Orthologues: chimpanzee CDH4 (99% identical), macaque CDH4 (99% identical), dog CDH4 (94% identical), pig CDH4 (93% identical), rat Cdh4 (93% identical), mouse Cdh4 (92% identical), guinea pig CDH4 (92% identical), tropical clawed frog cdh4 (74% identical), zebrafish cdh4 (68% identical). Paralogues in human: CDH2 (65% identical), CDH1 (45% identical), CDH3 (39% identical), CDH15 (36% identical), CDH11 (31% identical), CDH6 (31% identical), CDH10 (30% identical), CDH7 (30% identical), CDH9 (30% identical), CDH13 (30% identical), CDH18 (30% identical), CDH8 (30% identical), and 21 more.
Diseases named in the same sentence as CDH4 in open-access papers:
CDH4 is named in the same sentence as 70 diseases in open-access papers, as found by Europe PMC text mining. Sharing a sentence is not in itself a finding about the gene and the disease. The quoted sentences say what the papers report.
osteosarcoma (10 papers, 2018 to 2025). A usually aggressive malignant bone-forming mesenchymal neoplasm, predominantly affecting adolescents and young adults. "CDH4 (R-Cadherin) has been previously found amplified in 43.6% of osteosarcomas, and its overexpression was associated with metastasis and a poor prognosis." (PMID 34572755, 2021). "The transcriptional level of CDH4 may serve as an effective diagnostic and prognostic biomarker for renal cell carcinoma patients, as it is a novel determinant of osteosarcoma tumorigenesis and metastasis." (PMID 38283146, 2023). "Similarly, CDH4 deficiency impacts the invasion of human osteosarcoma cells, and epithelial ovarian cancer (EOC) invasion is mediated by ITGAM." (PMID 34105233, 2021). "Conversely, in osteosarcoma and glioblastoma, there is a significant up-regulation of CDH4 expression." (PMID 38402159, 2024). "In osteosarcoma, overexpression of CDH4 triggers the activation of c-Jun through the JNK pathway and fosters tumor xenograft growth and lung colonization." (PMID 38402159, 2024). "Although the role of CDH4 in tumors remains elusive, several studies have indicated that CDH4 can promote tumorigenesis and metastasis in osteosarcoma and bladder cancer." (PMID 38402159, 2024). "In osteosarcoma, CDH4 was shown to activate c-Jun via the JNK pathway and improve self-renewal ability to promote tumorigenesis and metastasis." (PMID 37237299, 2023). "Nevertheless, some researches also support an oncogenic function of CDH4, such as in high-grade gliomas and osteosarcoma." (PMID 34289835, 2021). "In the process of urolithiasis, CaOx activated NADPH oxidase, producing ROS, via JNK pathway, which is activated by overexpression of CDH4 in osteosarcoma cells." (PMID 31036010, 2019). "Besides, CDH4 has been recently found to be overexpressed and to play key pro-tumour roles in osteosarcoma." (PMID 34488783, 2021). "A recent study showed that R-cadherin is overexpressed in SaOS-2, SJSA-1, and U2OS, and that the knock-down of CDH4 by shRNA in U2OS reduces migration and invasion of these osteosarcoma cell lines." (PMID 29805751, 2018). "We also performed transcriptome analysis (RNA-seq) of flavopiridol-treated osteosarcoma cells, which revealed significant changes in genes coding for proteins involved in cell-cell and cell-matrix adhesions, including cadherin 3 (CDH3) and 4 (CDH4)." (PMID 29805751, 2018).
gastric cancer (8 papers, 2016 to 2025). A primary or metastatic malignant neoplasm involving the stomach. "CDH4, codes for cadherin, and has been implicated in nasopharyngeal carcinoma and aberrant methylation of CDH4 promoter has been colorectal and gastric cancer." (PMID 27047539, 2016). "For instance, in epithelial cell-derived tumors such as breast cancer, gastric cancer, and colorectal cancer, the expression of CDH4 is suppressed due to hypermethylation of its promoter region." (PMID 38402159, 2024). "Taking advantage of tandem mass tag (TMT)-based quantitative proteomics, we identified a possible binding partner of β-catenin: R-cadherin (Cadherin-4), which was shown to be a tumor suppressor in breast, colorectal, and gastric cancer." (PMID 35954304, 2022). "Dependent on cell context, in most epithelial cancers like breast cancer, colorectal and gastric cancer, CDH4 is epigenetically silenced by promoter hypermethylation and commonly acts as a tumor suppressor." (PMID 34289835, 2021). "Conversely, aberrant methylation of the CDH4 gene promoter suggests that CDH4 may also function as a tumor suppressor gene in human nasopharyngeal, colorectal, and gastric cancer." (PMID 38402159, 2024). "CDH4 might be a tumor suppressor gene in various cancers, such as nasopharyngeal carcinoma, gastric cancer, and colorectal cancer." (PMID 28095912, 2017). "However, in some other cancers, such as nasopharyngeal carcinoma, gastric cancer, and colorectal cancer, CDH4 acted as anti-oncogene, CDH4 gene expression was downregulated." (PMID 28095912, 2017).
nasopharyngeal carcinoma (8 papers, 2015 to 2023). A carcinoma arising from the nasopharyngeal epithelium. "Some studies have shown that CDH4 is a tumor suppressor in nasopharyngeal carcinoma, gastrointestinal tumors, mammary tumors and lung cancer." (PMID 37237299, 2023). "In recent years, aberrant promoter methylation of CDH4 was detected in both gastrointestinal tumor and nasopharyngeal carcinoma, respectively, which demonstrated CDH4 methylation may be a common phenomenon in the process of tumorigenesis." (PMID 27029387, 2016). "CDH4 is aberrantly methylated in its promoter region in gastric and colorectal cancer and may act as an epigenetically silenced tumor suppressor in nasopharyngeal carcinoma." (PMID 26039411, 2015). "While the role of CDH4 in proliferation, cellular motility, invasion, and metastasis in a Rho GTPase-dependent manner has been described previously in the context of gastric and nasopharyngeal carcinoma, there are no reports linking CDH4 with oncogenic KRas signaling." (PMID 27894102, 2016).
breast cancer (7 papers, 2016 to 2023). A primary or metastatic malignant neoplasm involving the breast. "We supposed that high mRNA expression levels of CDH4/11/12/13 were associated with breast cancer and poor survival." (PMID 36315446, 2022). "CDH4 hypermethylation was significantly associated with increased risks for breast cancer in peripheral blood leukocyte DNA." (PMID 36315446, 2022). "Furthermore, results of the bc-GenExMiner database demonstrated that increased CDH4/12/13 expressions were associated with basal-like breast cancer, and increased CDH1/2/11 expressions suggested a high SBR grade status in patients." (PMID 36315446, 2022). "In the METABRIC dataset, CDH1 acted more like a TSG, and CDH4 acted like an oncogene in breast cancer." (PMID 36315446, 2022). "Collectively, our results demonstrated that UBR7 is a H2B E3 ubiquitin ligase that suppresses triple-negative subtype of breast cancer by activating CDH4/R-cadherin expression and inhibiting the canonical Wnt/β-catenin signaling pathway." (PMID 30923315, 2019). "Typically, cancer driver genes NFIX and CDH4 may act as methylation biomarkers for early detection for breast cancer and gastrointestinal tumorigenesis." (PMID 34323415, 2021). "Although we showed that UBR7 prevents metastatic colonization and represses genes that are crucial for breast cancer metastasis by targeting CDH4, other downstream pathways and target genes may also have important roles." (PMID 30923315, 2019). "Here, the authors show that UBR7 PHD finger is a H2BK120 monoubiquitin ligase that acts a tumour suppressor in breast cancer by suppressing gene expression for EMT, while promoting expression of CDH4 which restrain WNT/β-cat pathway." (PMID 30923315, 2019). "Furthermore, CDH4 expression exhibited consistent patterns to UBR7 in matched “normal” and “malignant” breast cancer cell lines." (PMID 30923315, 2019).
lung carcinoma (6 papers, 2017 to 2024). "CDH4 is responsible for encoding R-cadherin protein, which is pivotal in cell migration, adhesion, and tumorigenesis, and the expression of CDH4 in lung cancer tissues is significantly lower than that in adjacent tissues." (PMID 37670265, 2023). "We have shown in this study that knockout of GluIIβ from lung cancer cell line significantly decreased the expression of CDH2 as well as the reduction of many other cell surface proteins including CDH4, PD-L1 (B7-H1) and PD-L2 (B7-DC)." (PMID 38245670, 2024). "In conclusion, our study first reported that the expression levels of CDH4 mRNA were decreased in the lung cancer tissues." (PMID 28095912, 2017). "The relative value of CDH4 mRNA in lung cancer tumor tissues (mean 0.15) was lower than those of normal tissues (mean 0.32, P < 0.05)." (PMID 28095912, 2017). "This study analyzed the relationship of CDH4 mRNA expression with lung cancer." (PMID 28095912, 2017). "What is more, the relative CDH4 mRNA value was decreased in the lung cancer tissues." (PMID 28095912, 2017). "In lung cancer, our study suggested that CDH4 might serve as tumor surpressor gene, though more research need to be conducted." (PMID 28095912, 2017). "However, the CDH4 expression in lung cancer and its’ correlation with lung cancer clinical characteristics were still unclear." (PMID 28095912, 2017). "Our results suggested that CDH4 might be a putative tumor suppressor gene (TSG) in lung cancer." (PMID 28095912, 2017). "Moreover, CDH4 may function as a potential tumor suppressor gene in lung cancer." (PMID 38283146, 2023). "The relative CDH4 mRNA value was remarkably decreased in lung cancer tissues compared with noncancerous tissues (P = 0.001)." (PMID 28095912, 2017). "In our research, we first conducted RT-PCR examining CDH4 mRNA expression in 142 paired cases of lung cancer tissues and noncancerous tissues." (PMID 28095912, 2017). "Real time PCR was applied to detect CDH4 mRNA transcription in 142 paired cases of lung cancer and noncancerous regions." (PMID 28095912, 2017). "In this study, we first investigated the transcription levels of CDH4 mRNA in lung cancer tissues and paired noncancerous regions, to explore the relationship between CDH4 mRNA and clinical characteristics, and attempted to illustrate that CDH4 was a tumor suppressor gene (TSG) in lung cancer." (PMID 28095912, 2017).
colorectal cancer (5 papers, 2015 to 2022). A primary or metastatic malignant neoplasm that affects the colon or rectum. "In 2004, Elenma Mitto firstly found CDH4, the encoding gene of R-cadherin, was dominant methylated in colorectal cancer and GC." (PMID 27029387, 2016). "Genes coexpressed with CDH4 were correlated with “Protein folding and maturation POMC processing”, “Beta-catenin-dependent transcription regulation in colorectal cancer”, and “Cell adhesion_ECM remodeling”." (PMID 36315446, 2022).
glioma (4 papers, 2016 to 2025). A benign or malignant brain and spinal cord tumor that arises from glial cells (astrocytes, oligodendrocytes, ependymal cells). "Our results on patient-derived glioma cells demonstrate a positive correlation between Cdh4 expression levels and the loss of cell–cell contact inhibition of proliferation controls that allows cells to proliferate over confluence." (PMID 31426573, 2019). "In a previous work on a glioma model in mouse, we demonstrated that Cdh4 is necessary to sustain cell infiltration and proliferation in vitro and in vivo by overcoming both CIP and CIM mechanisms." (PMID 31426573, 2019). "The results showed that Cdh4 is necessary for glioma invasion and for the maintenance of the tumorigenic potential of these glioma cells." (PMID 31426573, 2019). "In the present study, to elucidate the role of Cdh4 on glioma cells migration, we extended our analysis in patient-derived glioblastoma initiating cells (GIC)." (PMID 31426573, 2019). "In our previous work on murine glioma cells we found a correlation between Cdh4 expression and ERK phosphorylation." (PMID 31426573, 2019). "Considering our previous data on the murine glioma model showing the role of Cdh4 in overriding the mechanism of CIP, we tested the ability of human GIC cultures to proliferate over confluence forming 3D foci." (PMID 31426573, 2019). "We previously demonstrated that Cdh4 can compete with Cdh2 for membrane localization in mouse glioma cells, inducing a cadherin switch similar to that described in the EMT process occurring during epithelial tumor progression." (PMID 31426573, 2019). "Only GBM23, the glioma culture with the lowest Cdh4 expression level, shows Cdh2 protein localization in the cell-cell junction region forming septa between adjacent cells." (PMID 31426573, 2019). "Our previous work demonstrated that Cdh4 is necessary for the maintenance of the full malignant phenotype in a murine model of glioma." (PMID 31426573, 2019). "In particular, we chose three GICs between the group of Cdh4 high-expressing gliomas: GBM-05, which has the lowest expression level in the group, GBM-06, which has an intermediate value and GBM-07, which has the highest expression level." (PMID 31426573, 2019). "Our results showed that, although Cdh4 silenced glioma cells can proliferate and infiltrate the brain parenchyma, these abilities result highly impaired." (PMID 31426573, 2019). "All these data suggest that Cdh4 could have a role in the acquisition of a malignant phenotype in gliomas." (PMID 31426573, 2019). "Moreover, the silencing of Cdh4 by artificial microRNAs induced a decrease in the infiltrative ability of human glioma cells both in vitro and in vivo." (PMID 31426573, 2019). "Overall our data demonstrated that Cdh4 could be a useful prognostic marker since its expression correlates with a shorter survival time for glioma patients." (PMID 31426573, 2019). "In the present study, we tested the role of Cdh4 in human gliomas." (PMID 31426573, 2019). "To test whether Cdh4 has a role in promoting glioma cells infiltration, we performed an in vitro wound healing assay scratching confluent cultures of both control and Cdh4 silenced GICs." (PMID 31426573, 2019). "Moreover, a metadata analysis on public datasets showed that Cdh4 expression level correlates with a shorter patients’ survival, suggesting for this protein an oncogenic role also in human gliomas." (PMID 31426573, 2019). "Moreover, our results showed that, although Cdh4 silenced glioma cells can proliferate and infiltrate the brain parenchyma, these abilities result impaired." (PMID 31426573, 2019). "We therefore checked whether Cdh4 is necessary for glioma cells infiltration in the brain parenchyma." (PMID 31426573, 2019). "The AKT (Protein Kinase B) pathway is not activated in our GIC cultures since the phosphorylated form of AKT is almost absent in these cells and it is not influenced by Cdh4 modulation as for the murine gliomas." (PMID 31426573, 2019).
glioma (continued). "Two of these genes (EMILIN-3 and CDH4) have never been reported in the context of glioma research so far." (PMID 27782828, 2016). "Our data suggest that Cdh4 is a useful prognostic marker for glioma and, although down-regulation is not sufficient to fully inhibit glioma invasion as was in the murine model, we showed a partial rescue of CIM mechanisms in vitro and a reduced migratory activity in vivo." (PMID 31426573, 2019). "Only few cells have left the injection site and are still in the nearby (data not shown) so we could not analyze the effect of Cdh4 downregulation on these two gliomas in vivo." (PMID 31426573, 2019). "However, our data showed that in human gliomas Cdh4 silencing is not sufficient to completely inhibit the infiltrative phenotype and, possibly, other mechanisms contribute to this process." (PMID 31426573, 2019). "To analyze whether Cdh4 silencing is sufficient to restore CIP, we cultured the three downregulated GIC cultures over confluence and found that Cdh4 downregulation does not impair the ability of glioma cells to growth over confluence forming 3D foci in vitro." (PMID 31426573, 2019).
glioblastoma (3 papers, 2018 to 2021). The most malignant astrocytic tumor (WHO grade IV). "Overall, we conclude that in human glioblastoma, Cdh4 can also actively contribute in regulating cell invasiveness and malignancy." (PMID 31426573, 2019). "In conclusion, we can affirm that Cdh4 is able to facilitate human glioblastoma cells to overcome CIP and CIM enhancing tumor proliferation and invasion." (PMID 31426573, 2019). "In this work we focused on the role of Cdh4 in human glioblastoma." (PMID 31426573, 2019). "Similarly, CDH4 is an important driver of metastasis in glioblastoma." (PMID 34572755, 2021).
lymph node metastasis (3 papers, 2016 to 2024). "According to the IHC score of CDH4, a remarkable association of CDH4 expression with lymph node metastasis (LNM) was discerned (P = 0.017)." (PMID 38402159, 2024). "Furthermore, the overexpression of CDH4 in tumor tissues is associated with lymph node metastasis in PTC patients." (PMID 38402159, 2024). "Furthermore, the overexpression of CDH4 in tumor tissues is significantly associated with lymph node metastasis in PTC patients." (PMID 38402159, 2024).
thyroid cancer (3 papers, 2021 to 2023). "In particular, Gene Set Enrichment Analysis (GSEA) of CDH4 using gene expression data from the TCGA database also validated that CDH4 is involved in processes such as adherens junction and extracellular matrix-receptor interaction in thyroid cancer." (PMID 34289835, 2021). "We found that the expression of CDH4 is higher in cholangiocarcinoma (CHOL), Colon adenocarcinoma (CAOD), KIRP (Kidney renal papillary cell carcinoma), KIRC (Kidney renal clear cell carcinoma), THCA (Thyroid carcinoma) and HNSCC than normal tissues adjacent to the cancer." (PMID 37237299, 2023).
colon cancer (2 papers, 2013 to 2022). "A bioinformatics analysis identified differentially methylated CDH4 in human colon cancer samples." (PMID 36685967, 2022). "Among the group of the most consistently hypermethylated genes in both human colon cancer and mouse intestinal adenoma (48 genes), we found Cdh4, Crabp1, Crmp1, Dbc1, Duox1, Grm7, Hand1, Hs3st2, Pcdh17 and Pdpn, which have previously been suggested as cancer biomarkers." (PMID 23408899, 2013).